INS (insulin)
Diseases named in the same sentence as INS in open-access papers (continued):
Sharing a sentence is not in itself a finding about the gene and the disease.
Insulin resistance (continued). "Measures of insulin sensitivity indicated insulin resistance in men, and insulin resistance was associated with alterations in the lipid profile and elevated serum levels of C-peptide and GIP18, which are known to be associated with insulin resistance." (PMID 31941993, 2020). "While activation of the hexosamine pathway has been linked to the development of insulin resistance, inhibition of this pathway has been linked to an increase in insulin sensitivity." (PMID 32630335, 2020). "These have been shown to be a major cause for reduced insulin sensitivity and hepatic insulin resistance." (PMID 33013688, 2020). "Recently, it has been demonstrated that complete mutation in CEACAM1 gene (Ccl-/−) brings to impartments of insulin clearance causing hyperinsulinemia and limited insulin resistance." (PMID 32326243, 2020). "Relative insulin resistance is proposed as one of the contributing mechanisms, caused by antagonising effects of stress mediators that impair insulin-regulated glucose uptake." (PMID 31953778, 2020). "Inactivity, type 2 diabetes and obesity are associated with insulin resistance, while regular physical exercise improves glucose uptake and insulin sensitivity." (PMID 31980607, 2020). "Insulin resistance is a state of a weakened response of tissues such as skeletal muscle, adipose tissue, and liver to insulin, which causes an increase in blood glucose levels." (PMID 33322719, 2020). "Circulating insulin is one of primary blood phenotypes in assessing insulin function and its elevation is the hallmark of insulin resistance." (PMID 33322303, 2020). "This review aims at revisiting renal insulin actions and clearance and to address the association of kidney dysmetabolism with hyperinsulinemia and insulin resistance, both highly prevalent phenomena in modern society." (PMID 32850773, 2020). "The methylation level of PGC1-α is also associated with fasting blood glucose, fasting insulin levels, peripheral insulin resistance, and the homeostasis model assessment of insulin resistance (HOMA-IR)." (PMID 32577122, 2020). "The insulin sensitivity-promoting properties of adiponectin are well-known, and are exemplified by the development of insulin resistance in adiponectin-deficient mice, and the preservation of insulin sensitivity in adiponectin-overexpressing mice." (PMID 32158768, 2020). "Insulin resistance is caused by the impairment of insulin receptor-mediated signaling in insulin-sensitive organs, i.e., the liver, adipose tissue, skeletal muscles, brain, and so on." (PMID 33005239, 2020). "GDM is a heterogeneous disease with several underlying causes such as inadequate insulin secretion from pancreatic β-cells, insulin resistance, and genetic susceptibility." (PMID 32240385, 2020). "The dysfunction of insulin signaling will cause insulin resistance, which is a complex metabolic disorder that is closely linked to many pathways including lipid metabolism, energy expenditure, and inflammation." (PMID 33042976, 2020). "Several studies have associated this variability with the development of insulin resistance (IR), which is defined as a state whereby a normal concentration of insulin induces a decreased biological response in the insulin-sensitive tissues." (PMID 32842661, 2020). "Epidemiological studies have shown T2DM is associated with peripheral insulin resistance and central insulin signaling defects." (PMID 32575897, 2020). "The causal relation between hyperinsulinemia and insulin resistance is unclear, but the preponderance of evidence suggests that high levels of insulin initiate insulin resistance." (PMID 33167495, 2020). "Since the demand of insulin increases due to insulin resistance caused by obesity, beta-cell mass increases to adapt to these demands in the Caucasian population." (PMID 33339276, 2020).
Insulin resistance (continued). "A combination of peripheral insulin resistance (IR) and dysfunctional insulin secretion by pancreatic β-cells is implicated in the pathogenesis of type 2 diabetes mellitus (T2DM)." (PMID 33043822, 2020). "The concept of diabesity has been linked to impaired pathways of metabolic cell signaling as well as altered insulin signaling, i.e., insulin resistance (IR), which upsurges the risk of developing type 2 diabetes (T2D)." (PMID 33113859, 2020). "LCN-2 deficient mice show insulin-sensitive metabolic properties by inhibition of arachidonate 12-lipoxygenase, which is related to insulin resistance and inflammation." (PMID 32982804, 2020). "In patients with GHD, increased adipose tissue and decreased muscle tissue lead to obesity and reduced exercise capacity, which lowers insulin sensitivity and subsequently causes insulin resistance and impaired glucose tolerance." (PMID 32328036, 2020). "Adipocyte size has been shown as an independent risk factor for insulin resistance and reduction in fat cell size has been shown to be associated with improved insulin sensitivity at 1–2 years after RYGB." (PMID 31983031, 2020). "In order to enhance the power to identify significant differences between controls and DM, GDM and T2DM were combined into one group since GDM is associated with both insulin resistance and impaired insulin secretion and shares the same risk factors with T2DM." (PMID 32972433, 2020). "Clinical findings and numerous epidemiological studies also support the beneficial role of insulin on cognition, and now, it is well‐established that the insulin resistance associated with T2DM can also lead to vascular dementia." (PMID 32170854, 2020). "Persistent hyperinsulinemia, an above normal level of insulin in the blood, is associated with insulin resistance." (PMID 32576931, 2020). "This stimulation of pro-inflammatory factors will aggravate insulin resistance and glucose intolerance linked with obesity due to the dysfunction of insulin signaling cascade activation and glucose transporter recruitment to the membrane." (PMID 33353562, 2020). "LPA, MVPA, and daily steps associated with better insulin sensitivity and favorable plasma lipid profile, when adjusted for age, sex and BMI, whereas greater proportion of SB associated with insulin resistance and unfavorable lipid profile." (PMID 33239818, 2020). "The most consistent associations across sensitivity analyses were with fasting insulin levels, insulin resistance and height." (PMID 32548700, 2020). "High fat associated with high GI has been shown to induce insulin resistance, while the same fat content with a low GI improved insulin sensitivity." (PMID 33003562, 2020). "It has long been known that plasma amino acid profiles are changed during obesity and are linked with changes in insulin secretion and the development of insulin resistance." (PMID 32827096, 2020). "The increased FFA concentration interferes with the insulin signaling causing peripheral insulin resistance or reduces the accessibility of insulin to skeletal muscles ultimately reducing the glucose transport towards muscles." (PMID 32708684, 2020). "Insulin treatment can not only lead to desensitization of insulin receptors but can also cause increased appetite and weight gain and worsen insulin resistance." (PMID 33167495, 2020). "The role of insulin in aging has been assessed by a body of literature stating one major finding that insulin sensitivity is associated with longevity while insulin resistance is associated with higher mortality." (PMID 32138778, 2020). "Triglycerides, FBG, insulin, and homeostasis model assessment of insulin resistance were inversely associated with 25(OH)D concentrations (p<0.05) in both sexes." (PMID 32071197, 2020). "Male Syrian hamsters fed a 60% fructose diet for six weeks developed hippocampal insulin resistance associated with a significant attenuation of insulin-induced long-term depression." (PMID 33374894, 2020).
Insulin resistance (continued). "Insulin resistance (IR) is a pathophysiological state caused by a gradual decline in the insulin responsiveness in peripheral tissues, including skeletal muscle, adipose tissue, and liver." (PMID 32290082, 2020). "Insulin resistance also causes the body to resort to a state of high insulin levels, which in turn causes the body to overexpress insulin degrading enzymes (IDE) which are designed to break down excess insulin." (PMID 33192493, 2020). "As overweight/obesity is linked to insulin resistance, the beta-cells need to secrete more insulin/C-peptide to maintain the same glucose levels as in lean subjects." (PMID 32775460, 2020). "For instance, low-calories and low carbohydrate diets that aim to reduce body weight, a well-known associated factor of insulin resistance had beneficial effects on insulin sensitivity and blood sugar level." (PMID 32899917, 2020). "A combination ofmetformin and insulin given to critically ill patients reducedthe incidence of insulin resistance, adverse effects associatedwith high-dose insulin therapy, as well as inflammatorycytokines production." (PMID 31376317, 2020). "The combination of genetic factors associated with impaired insulin secretion, insulin resistance, environmental factors, including overeating, aging, obesity and lack of exercise, typically accounts for T2D." (PMID 33114564, 2020). "Insulin resistance is usually associated with the development of an inflammatory state and can occur as a result of insulin modulation, deactivation of the insulin receptor complex, defect in the signal transduction modulations." (PMID 32694996, 2020). "Obesity causes insulin resistance, albeit less in females, which can increase insulin and therefore SNA." (PMID 32160920, 2020). "In American adults, a “calorie dense” diet was positively associated with fasting insulin levels and insulin resistance based on homeostasis model of insulin resistance (HOMA-IR) scores." (PMID 32650448, 2020). "Insulin resistance and compensatory hyperinsulinemia have been shown to be associated with an increased risk of developing type 2 diabetes, and hyperglycemia of diabetes is caused by impaired insulin secretion and insulin resistance." (PMID 33255783, 2020). "Women are distinctly different from men with regard to the actions of insulin and the susceptibility to develop insulin resistance." (PMID 32754618, 2020). "Roles of prolactin on both insulin resistance and decreased insulin secretion (i.e., inverse association with C-peptide levels) are consistent with our finding of a positive association between prolactin and GDM risk." (PMID 32180760, 2020). "Obesity‐related insulin resistance linked to diet leads to CRC through the growth‐promoting effect of elevated levels of insulin, glucose and/or triglycerides (Bruce, Wolever, & Giacca, 2000)." (PMID 31903726, 2020). "The resulting hypersecretion of insulin can cause poor insulin signaling and clearance at the liver, leading to hyperinsulinemia and insulin resistance." (PMID 32582035, 2020). "It is well known that insulin resistance and deficiency in insulin production from pancreatic β-cells are the main characteristics of DM." (PMID 33228164, 2020). "Obesity/metabolic syndrome is always associated with insulin resistance, which is defined as the impaired sensitivity of organs/tissues such as the liver, skeletal muscle and adipose tissues to the action of insulin and can be induced by HFD." (PMID 32244807, 2020). "This mutation results in the reduction of insulin release and insulin resistance and leads to persistent hyperglycemia, which in turn causes mitochondrial dysfunction and reduces insulin release." (PMID 32733635, 2020). "Inflammasome activation has been implicated in the development of insulin-resistance in adipose tissue of obese patients through impairment of insulin signaling." (PMID 33126679, 2020).
Insulin resistance (continued). "Dietary chromium has been shown to reduce fat deposition and improve insulin action whereas dietary fat can increase fat deposition and cause insulin resistance." (PMID 32961883, 2020). "On the other hand, the loss of muscle mass leads to less insulin-responsive target tissue, resulting in a severe condition of insulin resistance." (PMID 32982969, 2020). "Overall, deficiency of Fxr results in insulin resistance and diminished insulin secretion in pregnancy." (PMID 32661285, 2020). "The NSY mouse shows both impaired insulin secretion and insulin resistance caused by multiple genes." (PMID 32703163, 2020). "Obese people generally have insulin resistance, and this is often associated with elevated levels of circulating insulin." (PMID 32785012, 2020). "Advancement in age is also associated with a higher incidence of insulin resistance and impaired insulin secretion as a result of impairment in the functioning of the islet cell, which negatively impacts glycemic control and consequently, CKD development." (PMID 33327258, 2020). "Pro-inflammatory cytokines such as IL-6 and TNF-α are implicated to promote insulin resistance by interfering with the insulin signaling pathway, leading to the pre-clinical manifestation of T2DM." (PMID 32694996, 2020). "This metabolic disorder is characterized by increased sugar concentration in the blood cause by impaired insulin secretion or insulin resistance." (PMID 33255297, 2020). "Palmitate induced insulin resistance resulted in a much lower electrical resistance compared to basal conditions, and a complete loss of response to insulin stimulation." (PMID 33458251, 2020). "Our study has replicated the association of rs7403531 with insulin resistance, which was consistent with a previous study which reported that rs7403531 had been associated with T2D and higher insulin in Chinese Hans." (PMID 32260174, 2020). "It is well known that fasting insulin is associated with insulin resistance, which is an essential factor in developing type 2 diabetes." (PMID 31973038, 2020). "Myo-inositol supplementation was associated with lower insulin levels, glucose levels, and insulin resistance when compared with placebo, metformin, or estrogen treatments." (PMID 32587614, 2020). "Abnormal insulin action, known as insulin resistance (IR) is a main feature underlying development of type 2 diabetes." (PMID 32957570, 2020). "CTRP12 exerts a beneficial effect on glucose and insulin metabolism and plays a potential detrimental role in atherosclerosis via its association with insulin resistance, decreased high-density lipoprotein cholesterol, and increased BMI." (PMID 32468164, 2020). "The main findings of the present study suggest that BFox is associated with better insulin sensitivity in sedentary middle-aged adults, whereas BCHox is positively related to insulin resistance." (PMID 32340248, 2020). "As described in detail previously, the enlarging adipose tissue in obese subjects synthesizes and secretes hormones and proteins like leptin, adiponectin and TNF-α, which modify insulin secretion and sensitivity, causing insulin resistance." (PMID 32947869, 2020). "One of the typical features of type 2 diabetes is high glucose levels in the blood caused by the loss of insulin sensitivity or the increase in insulin resistance (IR) in the cells." (PMID 33489029, 2020). "The present study aimed to investigate the effects of berberine on insulin resistance, and to clarify the underlying mechanism of berberine enhancing insulin sensitivity and restoring metabolic homeostasis by activating AMPK signalling." (PMID 32393087, 2020). "Beta cell dysfunction, impaired insulin secretion, and increased insulin resistance cause the chronic dysregulation of the hyperglycemia state and are critical in pathophysiological determinants of the disease’s progression and pathogenesis." (PMID 32823525, 2020).
Insulin resistance (continued). "With the univariate fit, BMI was associated with triglycerides (p < 0.001) and insulin (p < 0.00001) concentrations, insulin resistance (p < 0.00001) and CG rs1421085 and rs3751723 haplotype (p = 0.01) after adjusting for gender and age." (PMID 32651404, 2020). "Insulin action on peripheral metabolic tissues decreases as a result of deficient insulin secretion in type 1 diabetes or insulin resistance combined with insufficient insulin secretion in type 2 diabetes." (PMID 33150239, 2020). "The increased level of free fatty acids results in suppression of insulin clearance and is closely associated with insulin resistance in obese individuals." (PMID 32478050, 2020). "The assessment of HOMA indices in serum samples showed that piperine and sitagliptin (positive control, PC) caused significant alterations of insulin resistance, β cell function, and insulin sensitivity." (PMID 33737876, 2020). "Type 2 diabetes (T2D) is characterized by persistent hyperglycemia, deficient insulin secretion, or insulin resistance and has become a global public health concern over recent decades." (PMID 33150187, 2020). "Insulin resistance is a complex pathological state of inappropriate cellular response to insulin hormone in insulin dependent cells, and it is a common risk factor in metabolic disorder associated diseases." (PMID 32660483, 2020). "Reduced insulin-activation of skeletal muscle GS during a hyperinsulinemic-euglycemic clamp is a hallmark of insulin resistance and type 2 diabetes." (PMID 33375333, 2020). "Patients with T2DM with high insulin demand have severe insulin resistance and are at high risk of cardiovascular disease." (PMID 31859911, 2020). "As JNK deficiency in the brain improves insulin sensitivity, palmitate presumably induces other kinases in hypothalamic neurons, which are instrumental for palmitate-induced neuronal insulin resistance." (PMID 32456175, 2020). "These inquiries are particularly important in the context of the pathophysiology of type 2 diabetes, in which hyperinsulinemia, an imbalance in insulin/glucagon levels, and insulin resistance are associated with the development and progression of the disease." (PMID 32698380, 2020). "In the NHENES, serum bicarbonate concentration and serum anion gap were inversely and positively associated with fasting insulin levels and Homeostasis Model Assessment for Insulin Resistance (HOMA-IR), respectively." (PMID 32486113, 2020). "The development of MS is associated with obesity, inflammation, and impaired tissue susceptibility to insulin action (insulin resistance)." (PMID 33344442, 2020). "Obesity-associated insulin resistance in insulin-target tissues including the liver, skeletal muscle and adipose tissue is an early clinical feature of the development of Type 2 diabetes." (PMID 32911464, 2020). "These were positive quadratic (J-shaped) associations, suggesting that those with high basal insulin resistance or β-cell function had a larger magnitude of reduction in insulin tAUC between SIT and EX+BR." (PMID 33308235, 2020). "T2DM results from progressive loss of insulin secretion, which is typically combined with various degrees of insulin resistance." (PMID 32164656, 2020). "On the contrary, elevated FFA was linked with the development of insulin resistance, defects in insulin secretion, nonalcoholic fatty liver disease, and metabolic syndrome." (PMID 32370212, 2020). "We observed positive associations of BMR with plasma insulin and the homeostatic model assessment of insulin resistance index (HOMA; all p < 0.05) which were attenuated or disappeared after controlling by sex, age, and/or lean mass." (PMID 32340248, 2020). "The MECR protein reduction was associated with insulin resistance and the protein restoration was associated with improvement of insulin sensitivity by BBR in the DIO mice." (PMID 32440681, 2020).